SCGB1A1 (secretoglobin family 1A member 1)
Diseases named in the same sentence as SCGB1A1 in open-access papers (continued):
Sharing a sentence is not in itself a finding about the gene and the disease.
chronic bronchitis (1 paper, 2021). A type of chronic obstructive pulmonary disease characterized by chronic inflammation in the bronchial tree that results in edema, mucus production, obstruction, and reduced airflow to and from the lung alveoli. "Low circulating SCGB1A1 levels have been associated with higher risk for chronic bronchitis among smokers." (PMID 34564359, 2021). "To gain insight into the local expression of SCGB1A1 transcript and protein expression following tobacco smoke exposure, we exposed physiologically relevant bronchial (normal and chronic bronchitis like) mucosa models to CSC." (PMID 34564359, 2021). "Increased SCGB1A1 levels in the sham exposed chronic bronchitis-like model compared to that of normal bronchial mucosa may be explained by the addition of IL13 to induce mucous production." (PMID 34564359, 2021).
esophageal cancer (1 paper, 2020). A primary or metastatic malignant neoplasm involving the esophagus. "The results showed that EPHA5, LOC100506136, RGS7, THBS4, SCGB1A1, and DPEP1 were dysregulated between esophageal cancer and normal control in GSE13898 validation dataset (all, P<0.05)." (PMID 32068233, 2020).
mood disorder (1 paper, 2022). A cognitive disorder a disturbance in which the person's mood is hypothesized to be the main underlying feature. "Four of our 16 candidate proteins have previously been investigated in relation to mood disorders or suicide (FKBP5, FGFR2, SCGB1A1, and CD63), but most candidate proteins are novel to mood disorders and suicide research." (PMID 35697758, 2022).
systemic sclerosis (1 paper, 2015). A chronic disorder, possibly autoimmune, marked by excessive production of collagen which results in hardening and thickening of body tissues. "SCGB1A1 (CC16) can be used as a potential biomarker for PF in systemic sclerosis patients." (PMID 26559674, 2015).
tumor (61 papers, 2009 to 2025). "In this case, mutant beta catenin within Scgb1A1 + cells caused a distal cell fate change and enhanced tumor formation within Scgb1A1 + expressing cells." (PMID 35983994, 2022). "The role of p16 in suppressing spontaneous tumor formation in RB1-deficient lungs was investigated in vivo by generating double transgenic Scgb1a1-rtTA/tetCre mice wherein RB1 ablation was targeted to the lung epithelium in a p16+/− and p16−/− background." (PMID 28414317, 2017). "Taken together, the DNA methylation data supports the Club cell origin of labelled tumours from Scgb1a1 and Hopx lines." (PMID 35931677, 2022). "An associated elevation in Ninj1 and Nanog expression was also observed in tumor nodules in Scgb1a1-CreERTM;L-Ninj1Tg/+ and Sftpc-CreERT2;L-Ninj1Tg/+;KrasG12D/+ mice." (PMID 35395804, 2022). "This was also supported by the hypermethylation of the Scgb1a1 promoter in Club originated tumours, impairing the expression of this marker, and hypomethylation of the Sftpc promoter similar to that in normal AT2 cells, indicating the linage switch." (PMID 35931677, 2022). "Lineage tracing analyses following Ad-CMV-Cre administration have tracked the origin of murine LUSC tumours induced by activation of KrasG12D and Tgfbr2 ablation to SCGB1A1+ Club cells." (PMID 34354223, 2021). "In the LUAD-LUSC transition model driven by expression of KRASG12D along with STK11 depletion, tumours have been found to originate from SCGB1A1+ Club cells and SFTPC+SCGB1A1+ BASCs, as assessed by allograft assays following 3D organoid culture." (PMID 34354223, 2021). "Herein, we found that 5 genes (Shisa3, PADI1, LRP2, ANGPTL4 and ALOX15B) were upregulated and 4 genes (CXCL9, ADAMDEC1, SCGB1A1/CC10, HLA-G) were downregulated in PR tumor tissues compared to SD tumor tissues." (PMID 31801598, 2019). "However, in contrast to our AT2-derived tumor-initiation model, mutant beta catenin expression results in enhanced tumor formation within Scgb1A1+expressing cells." (PMID 35983994, 2022). "Microscopic analyses revealed that the number of tumor nodules (P = 0.0259), particularly those larger than 1 mm3, was significantly higher in Scgb1a1-CreERTM;L-Ninj1Tg/+ mice than it was in Scgb1a1-CreERTM;LSL-Ninj1Tg/+ mice (1 mm3 ≤ volume < 5 mm3: P < 0.001; volume ≥ 5 mm3: P = 0.0154)." (PMID 35395804, 2022). "To evaluate the anti-tumor effect of the BA derivatives in vivo, we used xenograft models and transgenic mice that develop spontaneous lung tumors following doxycycline treatment in Scgb1a1-rtTA/TetO-Kras4bG12D and Scgb1a1-rtTA /TetO-EGFRL858R mice." (PMID 25909174, 2015). "Conversely, it was also reported that decreased SCGB1A1 expression could contribute a tumor microenvironment permissive of inflammation and hence tumor progression." (PMID 23253434, 2012). "Notably the tumour sample contained very few cells still expressing the Club cell marker Scgb1a1." (PMID 35931677, 2022). "Interestingly, PORCN was expressed in a large percentage of SCGB1A1 tumor cells, too." (PMID 34249925, 2021). "IGKC, SCGB1A1 HSPB1, and FCGR3A were found to be differentially expressed in normal tissue compared with tumor and metastasis." (PMID 37335089, 2023). "To discern possible implications of the labelled AT2 cells in the Scgb1a1 model, we included all GFP+ cells from a second intermediate sample—4 weeks after Ad-EA—as well as all GFP+ tumour cells from late-stage tumour nodules and performed scRNA-seq." (PMID 35931677, 2022). "While tumours mainly arose in the bronchi and bronchioles after targeting KRT14+ cells, they were restricted to peripheral locations when SCGB1A1+ or SFTPC+ cells were targeted." (PMID 34354223, 2021). "Immunofluorescence analysis of the xenograft tumour derived from one of these clones revealed cells expressing the Clara cell marker SCGB1A1, and cells expressing the goblet cell marker MUC5AC, in addition to p63-positive basal cells in the tumour tissue." (PMID 28380052, 2017).
tumor (continued). "Using our extensive pan-cancer NK cell atlas, we were able to generate a solely NK cell-derived, tissue-residency signature (atlas-TR: PSMA2, SLC5A3, CCL4L2, CLN3, SCGB1A1, AREG), which outperformed the conventional literature-derived TR signature across tissue and tumor type." (PMID 38956379, 2024). "Since a fraction of primary tumors exhibits the columnar cell phenotype, displaying the participation of non-ciliated columnar Clara cells in tumor formation, we analyzed the liver metastases for Clara cell marker, Scgb1a1." (PMID 29464089, 2018). "Although Sox2 is inducibly overexpressed in Scgb1a1-expressing cells, Scgb1a1 expression gradually decreases over time, eventually becoming completely absent at late stages of tumor development." (PMID 20548776, 2010). "No tumor nodules were observed in Scgb1a1-CreERTM;L-Ninj1Tg/+ mice at up to 1 year of age." (PMID 35395804, 2022). "Notably, tumours, irrespective of their cell of origin or the mouse line from which they originated, (Scgb1a1, Sftpc or Hopx), showed AT2-like methylation patterns." (PMID 35931677, 2022). "The prototypical member of the SCGB gene superfamily, SCGB1A1, also called Club cell secretory protein (CCSP), Club cell 10-kDa protein (CC10), or Club cell 16-kDa protein (CC16), is believed have anti-inflammatory, anti-fibrotic, immunomodulatory, and tumor suppressive functions." (PMID 26559674, 2015). "Immunostaining only detected expression of the club cell marker CC10 (also known as SCGB1A1) and not the AT1 marker AGER on tumor sections." (PMID 35577801, 2022). "Notably, the GFP+ tumours from Hopx, Scgb1a1 and Sftpc lines exhibited the same expression pattern: positive for SPC but negative for CCSP." (PMID 35931677, 2022). "SCGB1A1 and APOE may originate from stromal or immune cells rather than tumor epithelium." (PMID 41343534, 2025).
infection (33 papers, 2011 to 2025). The state of being infected such as from the introduction of a foreign agent such as serum, vaccine, antigenic substance or organism. "SARS-CoV-2 MA10 infection principally caused acute loss of distal airway club cell (Scgb1a1) and alveoli AT2 cell (Sftpc) marker expression, phenotypes consistent with SARS-CoV-2 cellular tropism in humans." (PMID 35857635, 2022). "Due to current non-availability of humanized ACE2 transgenic mouse model, we were unable to perform in vivo infection studies with SARS-CoV-2 in the setting of Scgb1a1 deficiency." (PMID 33117399, 2020). "As part of a study to identify transcriptional signatures associated with the MHV-68 M3 protein during infection, we identified a modulation of Scgb1a1 and Bpifa1 expression." (PMID 25531566, 2015). "Similarly, infection by Respiratory syncytial virus led to increased T-helper 2 cytokines, neutrophil chemokines and viral replication following Scgb1a1 deficiency whereas restoration of Scgb1a1 expression in the airway abrogated the viral persistence and lung inflammation." (PMID 33117399, 2020). "After inoculation of 105 PFU of SARS-CoV-2 to the K18-hACE2, SFTPB-hACE2, and SCGB1A1-hACE2 models, the peak viral titer was detected at 2 days post-infection and then gradually decreased." (PMID 36457995, 2022). "When used on the naive airways, these methods preferentially lead to infection of secretoglobin family 1A member 1 (SCGB1A1)+ Club cells in the distal airways, introducing bias for cell-of-origin investigation." (PMID 34354223, 2021). "Consistent with the cell restricted nature of the viruses, Sftpc (pro-SPC) expression was significantly enhanced in tumors initiated from AT2 cells, while elevated expression of Scgb1a1 (CC10) was detected in tumors following Ad5-CC10-Cre infection." (PMID 31519898, 2019). "Serpina5, Gzmd, Gzmg and Scgb1a1 are genes which transcription was negatively affected by the infection by both strains." (PMID 28273076, 2017). "Anatomical and temporal changes in Bpifa1 RNA and BPIFA1 protein expression following MHV-68 infection were similarly determined in the same wood mice used for SCGB1A1 analysis." (PMID 25531566, 2015). "Among other changes, this identified a significant upregulation of Scgb1a1 and Bpifa1 expression that was not only associated with expression of M3 but also with MHV-68 infection in general." (PMID 25531566, 2015). "In conclusion, CK14+ basal cells and SCGB1A1+ club cells in alveolar persistent bronchiolization foci expressed Ki67 until 112 dpi, suggesting ongoing proliferative activity long after the initial infection." (PMID 40021627, 2025). "The decrease in Sftpc and Scgb1a1 may be due to increased lung injury due to Zn‐D in the combined infection." (PMID 38163670, 2024). "However, SFTPB-hACE2 and SCGB1A1-hACE2 mice showed minimal clinical signs after infection." (PMID 36457995, 2022). "In our study, we found a decrease in the expression of Scgb1a1 in Zn‐D mice when compared to Zn‐R mice in response to H1N1 and MRSA combined infections." (PMID 38163670, 2024). "Cells were allowed to differentiate for 14 to 21 days prior to infection, and differentiation was confirmed by the endpoint PCR of differentiation markers MUC5AC, CBE1, SCGB1A1, BPIFA1 and TEKT1." (PMID 39772226, 2024). "This increase was accompanied by a dose-dependent decrease in FOXJ1 expression at both 48 and 72 h, and a decrease of SCGB1A1 at MOI 5 and 72 h after infection." (PMID 32637364, 2020). "Expression of the club cell-marker SCGB1A1 was also decreased by HRV-A16, but only at 72 h post-infection." (PMID 32637364, 2020). "Further analysis of MHV-68-infected animals showed that the levels of both protein and RNA for SCGB1A1 and BPIFA1 were decreased at day 7 post infection (p.i.)but increased at day 14 p.i. as compared with M3-deficient and mock-infected animals." (PMID 25531566, 2015).
infection (continued). "After infection with MHV-68, at both days 7 and 14 p.i. the trachea and bronchi showed a distribution of Scgb1a1 expression similar to that observed in control wood mice (not shown)." (PMID 25531566, 2015). "In summary, airway progenitors, in particular CK14+ basal cells and SCGB1A1+ club cells, dominated the cellular composition within the alveolar epithelial proliferation areas in the sub-acute and chronic phase after SARS-CoV-2 Delta infection." (PMID 40021627, 2025). "Following infection with K. pneumoniae, ablation of IL-17RA (interleukin-17 receptor A) in SCGB1A1 (secretoglobin family 1A member 1) expressing club cells significantly reduces CXCL5 levels, leading to reduced neutrophil recruitment and increased bacterial burden." (PMID 36829255, 2023). "On the other hand, GO enrichment analysis of the JXA1-downregulated mAb-PN9cx3-reversed genes did not identify an enriched pathway, but SCGB1A1 (Secretoglobin Family 1A Member 1) was downregulated after HP-PRRSV-JXA1 infection." (PMID 33726857, 2021). "However, the number of SCGB1A1+ club cells did not have any significant variation in the airways upon infection." (PMID 40021627, 2025).
adenocarcinoma (15 papers, 2010 to 2025). A common cancer characterized by the presence of malignant glandular cells. "Adenocarcinomas can be produced by Kras-G12D expression in AT2 cells expressing either Sftpc or Scgb1a1 (CCSP; CC10)." (PMID 33435818, 2021). "Overexpression of SLFN12 significantly reduced mRNA levels of the adenocarcinoma differentiation marker SCGB1A1 in all of the LUAD cells studied (HCC827, H23, and H1075) and in one LUSC cell line (H2170 cells) compared with treatment with AdCMV as a control." (PMID 32987632, 2020). "In our model, Sox2 overexpression in Scgb1a1-positive cells drives development of histologically well differentiated adenocarcinoma with significant squamous cell features including widespread expression of p63, FoxE1 and Desmoglein3." (PMID 20548776, 2010).
inflammation (15 papers, 2011 to 2024). Aberrant reaction of the microcirculation characterized by movement of fluid and leukocytes from the blood into extravascular tissues. "It is possible that decreased levels of SCGB1A1, a pulmonary surfactant protein that influences alveolar macrophage-mediated inflammation, may be linked to lung inflammation and epithelial integrity in participants with ARS33,50,51." (PMID 39632834, 2024). "Previous reports demonstrated that the levels of pro-inflammatory cytokines, IL-4, IL-5, and IL-13, and airway inflammation were suppressed in mice pre-treated with SCGB1A1 or SCGB3A2 in the OVA-induced allergic airway inflammation model." (PMID 26559674, 2015). "Therefore, to assess whether the increased AEC death associated with the expression of the Scgb1a1-Cre transgene could contribute to the exacerbated HDM-induced airway inflammation in FADDAEC-KO mice, we examined the responses of Scgb1a1-CreTg mice to HDM sensitization and challenge." (PMID 34045680, 2021).
cancer (14 papers, 2009 to 2025). A tumor composed of atypical neoplastic, often pleomorphic cells that invade other tissues. "Initially, the expression of cilia within the Sox2 overexpressing tumors seemed to confound Sox2 overexpression in Scgb1a1 positive cells as a model of human cancer." (PMID 20548776, 2010). "TGM4 and SCGB1A1 have been among down-regulated mRNAs in this type of cancer." (PMID 36497036, 2022). "Similarly, SCGB1A1, identified by The Cancer Gene Database as a cancer-related gene, was also filtered out of our gene set due to 100%- correct classification request of our procedure." (PMID 22369099, 2011). "Cancer cells in the S components upregulated SOX4 and CEACAM5 and downregulated pro-inflammatory factors such as SCGB1A1 and SFTPC in comparison with cancer cells in the GG components." (PMID 35874770, 2022). "It should be taken into consideration that SCGB1A1 was found in this study to have an over expression in both Cancer Never Smoker and Cancer Current Smoker." (PMID 26471143, 2015).
bacterial infection (2 papers, 2020 to 2024). "Anti-inflammatory effector function of SCGB1A1 has been well studied and it has been shown that viral and bacterial infections of lungs deficient in Scgb1a1 elicit greater inflammatory responses." (PMID 33117399, 2020). "SLPI, coexpressed with DMBT1 (coexpression score 0.078 from the GEO database, STRING), modulates inflammatory responses after bacterial infection, while OLFMA4 and SCGB1A1 are also associated with salivary gland function." (PMID 39580055, 2024).
respiratory diseases (1 paper, 2024). "The anti-inflammatory protein Clara Cell 10-kDa (CC10), also known as secretoglobin family 1A member 1 (SCGB1A1), shows promise in modulating respiratory diseases." (PMID 39078462, 2024).
SCGB1A1 also shares sentences with these, for which no sentence is quoted: adenoma (9 papers); acute respiratory distress syndrome (7); allergic rhinitis (7); idiopathic pulmonary fibrosis (7); sarcoidosis (7); Sepsis (6); silicosis (6); chronic lung disease (5); obliterative bronchiolitis (5); lung injuries (4); respiratory infections (4); allergic asthma (3); fibrosis (3); prostate carcinoma (3); airway hyperresponsiveness (2); Airway obstruction (2); Allergy (2); IgA nephropathy (2); lung tumor (2); Nephropathy (2); Obesity (2); respiratory failure (2); squamous cell carcinoma (2); acute lung injury (1); Anxiety (1); benign ovarian tumors (1); cardiovascular disease (1); childhood asthma (1); chronic eosinophilic pneumonia (1); colon cancer (1).
A further 30 diseases each share a sentence with SCGB1A1 in 1 paper.